IGF1 (insulin like growth factor 1)
Diseases named in the same sentence as IGF1 in open-access papers (continued):
Sharing a sentence is not in itself a finding about the gene and the disease.
Stroke (continued). "IGF1 supports axon and dendrite growth, and promotes neurogenesis in the aging brain as well as in conditions of injury such as stroke and TBI." (PMID 34095131, 2021). "IGF-1 supplementation in rodent models of middle cerebral artery occlusion and photothrombotic stroke reduces the size of infarcted tissue and the accompanying sensorimotor deficits, even when administered in the days after insult." (PMID 34887742, 2021). "This developmental function is seen again in aging or stroke, where production of IGF-1 by microglia promotes neurogenesis." (PMID 33642979, 2021). "Astrocytic insulin-like growth factor-1 (IGF-1) protected post-stroke BBB integrity and neurological function by shifting immune cells toward an anti-inflammatory profile in the ischemic environment." (PMID 34248961, 2021). "Additional work is needed to tease apart the impact of each cell type when exogenous IGF-1 is administered to protect against the damage induced by stroke and neurodegenerative diseases." (PMID 34887742, 2021). "In our previous studies, we reported that CD68+ microglia express IGF-1 in the brain of a stroke model." (PMID 32952570, 2020). "It has also been shown that induction of the insulin-like growth factor 1 ((IGF-1) which has neuroprotective properties in stroke) increased PrPC amounts through PI3K/Akt." (PMID 32630841, 2020). "Previous studies have demonstrated the effect of IGF-1, a primary mediator of GH, on improving motor function after stroke." (PMID 31963456, 2020). "Overexpression of IGF-1 by astrocytes through an AAV-mediated delivery improves outcome in a rat stroke model." (PMID 32952570, 2020). "Astrocyte-derived IGF1 has been shown to have neuroprotective effects in stroke and brain ischemia, as well as to protect against amyloid β-induced synapse and neuronal loss in Alzheimer’s disease." (PMID 33569054, 2020). "For instance, let-7f is capable of worsening the effects of stroke, by inhibiting insulin-like growth factor 1 (IGF-1) signaling." (PMID 32766248, 2020). "The downregulation of key PI3K-Akt activator IGF1 along with the upregulation of PI3K-Akt suppressors suggests stroke induced differential gene expression favoring reduced PI3K-Akt activation." (PMID 32629989, 2020). "In adult stroke models, galectin-3-positive microglial cells also produce neurotrophic factors, such as IGF-1, which also protect against damage after stroke." (PMID 31888302, 2019). "Low IGF1 resulted in a higher eCVR in RA patients (7.2% and 3.3%, p = 0.0063) and in stroke (9.3% and 7.1%, p = 0.033)." (PMID 31327319, 2019). "Post-stroke IGF-1 treatment reduced the infarct size by 34% and 38% in aged and adult rats, respectively." (PMID 31920629, 2019). "We previously showed, using this model, that SC injection of IGF-1 following stroke reduced infarct volume by 32% in 3-month-old rats and improved the NDS score." (PMID 31920629, 2019). "To our knowledge, we are the first to demonstrate that post-stroke systemic administration of IGF-1 reduces infarct size in aged rats." (PMID 31920629, 2019). "Post-stroke systemic injections of insulin-like growth factor-1 (IGF-1) exert neuroprotective effects in rats." (PMID 31920629, 2019). "In translational sessions, researchers found exogenous IGF-1 decreases brain lesions and prevents neurological deficits in a rodent stroke model." (PMID 31338023, 2019). "There was a statistically significant difference (p < 0.001) between the study groups regarding the serum IGF-1 with low mean among stroke cases." (PMID 30595648, 2018). "First, serum IGF-1 levels were only measured once after stroke onset, and additional measurements in the days after would have been of interest." (PMID 30595648, 2018). "The mean serum IGF-1 among stroke cases was (143.4 ± 12.6) ng/ml ranged between 98.6 and 173.9 ng/ml while among control group it was (156 ± 11.2) ng/ml ranged between 137.5 and 179.2 ng/ml." (PMID 30595648, 2018).
Stroke (continued). "The same trend has been observed between plasma IGF‐1 and the clinical recuperation and outcome after stroke." (PMID 28961383, 2017). "They suggest that during the neurorehabilitation after stroke, a high serum IGF‐1 correlates with recuperation of long‐term functions." (PMID 28961383, 2017). "Before stroke, the CR animals were characterized by a reduction in body weight, adipose tissue mass, circulating insulin, IGF1, and free fatty acids (FFA) levels as compared to the ad libitum‐fed animals." (PMID 28961383, 2017). "In our model, CR rats had significantly increased serum IGF1 levels in the first week after stroke that coincided with an accelerated recovery of body weight; IGF‐1 level was further maintained at day 14 by an increase in serum insulin levels." (PMID 28961383, 2017). "Usually, the serum level of IGF-1 in patients with stroke-derived intracerebral hemorrhage during admission (hospitalization) is lower than healthy controls, while VEGF and hepatocyte growth factor (HGF) are higher." (PMID 28373915, 2017). "Up-regulation of Gal-3 and IGF-1 in a subset of activated/proliferating microglial cells after stroke." (PMID 29312645, 2017). "Further randomized control trials are required to assess the effect of IGF-1 administration on stroke outcome in addition to the neuroprotective mechanisms of this hormone." (PMID 28435630, 2016). "In the studies with animal models of stroke, an increase in the expression of BDNF, GDNF, HGF, EGF, FGF-2, and IGF-1, as rapidly as 12 h after the insult and lasting until 5 days after stroke, has been described." (PMID 26607630, 2016). "Similar to the pattern seen at 2 days post stroke, brain IGF-1 levels at 5 days post stroke were only affected by ischemia (hemisphere) [F, 10.92, p = 0.0079], but not by NaB treatment [F, 0.74, p = 0.4098]." (PMID 27905989, 2016). "Risk of AD dementia is also associated with lower serum levels of IGF-1, and higher levels of IGF – 1 are associated with greater brain volumes and lower risk of dementia and stroke." (PMID 27875990, 2016). "Studies of endogenous expression of IGF-1 after adult stroke and elderly stroke found that after ischemic injury, IGF-1 serum levels decrease significantly." (PMID 25942688, 2015). "Serum IGF-1 levels have been proved to be depressed following acute stroke in the human being, while in rodent models brain IGF-1 levels resulted in increase in the perilesional stroke area, thus likely revealing a neuroprotective role." (PMID 26417600, 2015). "IGF-1 administered immediately after ischemia significantly reduced infarct volume in 9- to 11-month female rats 24 h after stroke." (PMID 25821444, 2015). "IGF-1 infusion following stroke, which prevents estrogen neurotoxicity in middle-aged female rats, altered the expression of two conserved IGF pathway regulatory miRNAs, Let-7f, and miR-1." (PMID 25821444, 2015). "Further studies examined the effect of post-stroke IGF-1 treatment on miRNA expression in middle-aged female rats." (PMID 25821444, 2015). "In vivo, stroke increases endogenous IGF-1 expression in rats, resulting in increased proliferation of neuronal and oligodendrocyte progenitors in the SVZ and DG." (PMID 25942688, 2015). "IGF-1 has also been shown to promote angiogenesis and myelination as well as neurogenesis and progenitor cell proliferation post-stroke in rats." (PMID 25942688, 2015). "Post-stroke IGF-1 treatment significantly downregulated 8 out of 168 disease-related miRNAs in tissue isolated 4 h after ischemia." (PMID 25821444, 2015). "At 24 hours post-stroke, IGF-1 treatment continued to inhibit selective pro-inflammatory markers, such as IL-6, the pleitrophic cytokine IL-13 and the chemoattractants CCL2 and GRO-KC." (PMID 24618563, 2014). "IGF-1 treatment, however, exerted a profound suppressive action on the stroke-induced immune response as early as 4h, decreasing the expression of both pro and anti-inflammatory cytokines." (PMID 24618563, 2014).
Stroke (continued). "Our results suggest that microRNA-223 is associated with acute ischemic stroke and possibly plays a role in stroke through up-regulating growth factor such as insulin-like growth factor-1 gene." (PMID 24708646, 2014). "This study determined the effect of post-stroke IGF-1 treatment, and used microRNA profiling to identify mechanisms underlying IGF-1’s neuroprotective actions." (PMID 24618563, 2014). "Post-stroke ICV administration of IGF-1 to middle-aged female rats reduced infarct volume by 39% when measured 24h later." (PMID 24618563, 2014). "Collectively, these data suggest that post-stroke IGF-1 treatment improves stroke outcome by minimizing the impact of stroke on blood brain barrier disruption and by shaping the post-stroke neuroinflammatory profile." (PMID 24618563, 2014). "MicroRNA analyses of ischemic tissue collected at the early post-stroke phase (4h) indicated that 8 out of 168 disease-related miRNA were significantly downregulated by IGF-1." (PMID 24618563, 2014). "IGF-1 induced Akt activation was preceded by a reduction of blood brain barrier permeability at 4h post-stroke and global suppression of cytokines including IL-6, IL-10 and TNF-α." (PMID 24618563, 2014). "Although IGF-1 appears neuroprotective in models of stroke and ischemic injury, this is the first study to assess neuroprotective actions of IGF-1 in a clinically relevant model of brain trauma." (PMID 23826235, 2013). "Our data also confirms that IGF-1 mRNA level is also increased in colony-OECs derived from stroke patients, suggesting a role for IGF-1 during the differentiation process of these cells." (PMID 23388410, 2013). "We, and other research groups previously showed that IGF-1 microinjections protected the brain from neurodegeneration following stroke." (PMID 22393433, 2012). "Our studies show that IGF-1 is neuroprotective to middle aged females even when administered 4 h post stroke, making this an attractive candidate for stroke therapy." (PMID 22393433, 2012). "This idea is supported by evidence that anti-Let7f treatment increased IGF-1 in microglia, harvested from the ischemic cortex 2d post-stroke." (PMID 22393433, 2012). "Estrogen is also neuroprotective for stroke and IGF-1 and estrogen interact to promote neuroprotection in stroke models." (PMID 22393433, 2012). "Exogenous IGF-1 reduces ischemic injury in many species, stimulates stroke-induced neurogenesis and promotes neuronal survival, neuronal myelination and angiogenesis." (PMID 22393433, 2012). "Further research should take into consideration not only the age of the subjects but also the dynamics of IGF-1 level before, during and after ischemic damage produced by stroke." (PMID 21110846, 2010). "Interestingly, pre-stroke IGF-1 levels were significantly and inversely correlated with grip strength recovery and with R/L lateralisation, showing that lower pre-stroke IGF-1 levels were associated with enhanced post-stroke recovery." (PMID 41094027, 2026). "IGF-1 may serve as a potential prognostic biomarker for long-term functional decline after stroke, but further large-scale prospective studies are needed to clarify causality and clinical applicability." (PMID 41586110, 2025). "IGF-1 is being explored as a potential biomarker and therapeutic target for stroke rehabilitation." (PMID 40142325, 2025). "Further well-designed longitudinal cohort studies and interventional trials are required to validate whether modifying IGF-1 signaling could influence long-term stroke prognosis." (PMID 41586110, 2025). "Lower circulating levels of insulin-like growth factor-1 (IGF-1) have been linked to a higher risk of stroke and poorer recovery outcomes, further emphasizing the importance of protective factors like APC in stroke prognosis." (PMID 40142325, 2025). "Notably, IGF-1 has been shown to not only bolster the survival of immature neurons but also aid in their maturation within the cortical parenchyma post-stroke." (PMID 41256775, 2025).
Stroke (continued). "Thus, intranasal delivery of IGF-1 has been studied in preclinical stroke models, where it effectively improved neurobehavioral outcomes and reduced infarct volumes." (PMID 41304786, 2025). "Direct intraventricular injection of IGF-1, administered 30 minutes after stroke induction, was found to reduce infarct size and improve functional outcomes, while local application of IGF-1 to the cerebral cortex achieved similar effects in reducing infarct size and enhancing neuron survival." (PMID 40789569, 2024). "In vivo stroke models also support this notion: IGF1 administration reduces infarct volume." (PMID 38502340, 2024). "IGF1 decreases with age, but remains an important neuroprotective agent as evidenced by clinical studies that, minus one exception, show elevated serum IGF1 levels correlating with improved functional outcomes in stroke patients." (PMID 38502340, 2024). "We confirmed that after the appearance of depressive phenotype in PSD rats, the level of IGF‐1 in their serum decreased significantly, which suggests that these changes may be related to the pathophysiology of depression symptoms in stroke patients." (PMID 38376033, 2024). "The increase in IGF‐1 levels due to inulin may indirectly provide new intervention targets for preventing depressive symptoms in stroke patients." (PMID 38376033, 2024). "Post-stroke IGF-1 treatment can decrease ischemic region and BBB permeability." (PMID 37358957, 2023). "Plasma concentrations of IGF-1 and the ratio of IGF-1/IGFBP-3 have been under clinical evaluation for their association with vascular diseases, i.e., age related cognitive status and stroke recovery." (PMID 36770687, 2023). "Changes in plasma IGF-1 concentrations at the one-set of stroke appear to be associated with mortality, but not functional recovery." (PMID 36770687, 2023). "The molar ratio of cGP/IGF-1 in plasma during the onset of stroke may be developed as a biomarker for predicting the ability of functional recovery in stroke patients." (PMID 36770687, 2023). "Changes in the cGP/IGF-1 molar ratio may assist in the prediction of the clinical outcome and management of stroke." (PMID 36770687, 2023). "Animal models of deficient circulating IGF-1 usually exhibit impaired blood–brain barrier integrity, and in a stroke mouse model, IGF-1 infusion reduced blood–brain barrier permeability and decreased infarct volume caused by middle cerebral artery occlusion in middle-aged female rats." (PMID 37358957, 2023). "The function of IGF-1 in stroke recovery has been well-documented." (PMID 36770687, 2023). "Stroke patients with a higher cGP/IGF-1 molar ratio have more favourable clinical outcomes." (PMID 36770687, 2023). "Below 26 nmol/L, the HR of stroke per 1-SD increment of IGF-1 was 0.93 (95% CI: 0.90–0.97)." (PMID 37608387, 2023). "Studies have shown a negative correlation between age and circulating IGF-1 levels in humans and rodents, associated with a high risk of stroke and poor outcomes." (PMID 37358957, 2023). "The association between IGF-1 concentrations and stroke were non-significant after adjusting for all potential confounders." (PMID 37608387, 2023). "The reduction of plasma IGFBP-3 in stroke patients could be a positive response to increase the amount of bioavailable IGF-1 in the circulation, whereas the low plasma cGP suggests a reduction of bioavailable IGF-1 in circulation during the onset of stroke." (PMID 36770687, 2023). "A study found that stroke patients and high IGF1/IGFBP-3 ratios had better outcomes." (PMID 37358957, 2023). "Post-stroke IGF-1 treatment can promote neural and vascular regeneration." (PMID 37358957, 2023). "However, after stroke, genomic ablation of Zfp580 led to a strongly reduced induction of paracrine Igf1 and Igfbp3 expression, whereas endocrine circulating Igf1 was increased." (PMID 35557964, 2022).
Stroke (continued). "Additionally, a rAAV-mediated increase in astrocytic IGF-1 reduced infarct volume and stroke-induced sensorimotor deficits in middle-aged female rats." (PMID 34570349, 2022). "Interestingly, higher circulatory levels of IGF-1 correlate with better long-term outcome in stroke patients." (PMID 35465399, 2022). "Inhibition of Zfp580 might be a new treatment target leading to increased activity of Igf1 to improve stroke outcome." (PMID 35557964, 2022). "In addition, plasma TNF-α and IGF-1 levels were increased and decreased in stroke patients, respectively, and miR-424 levels in both lymphocytes and neutrophils were negatively correlated with plasma TNF-α, IL-10, or IGF-1 levels." (PMID 36275741, 2022). "In summary, the effects of Igf1 and Igfbp3 on stroke outcome may be affected by their temporal and spatial regulation." (PMID 35557964, 2022). "Thus, Zfp580 deletion resulted in reduced paracrine cerebral Igf1 and Igfbp3 expression, increased endocrine Igf1 blood levels, and consecutively increased Igf1/Igfbp3 molar ratios 2 days after stroke." (PMID 35557964, 2022). "Besides, insulin-like growth factor 1 (IGF1) and aquaporin-4 (AQP4) decreased, while matrix metalloproteinase-9 (MMP9) heightened after stroke in brain ABCA1 deficiency mice." (PMID 35935038, 2022). "In conclusion, Zfp580 differentially controls paracrine and endocrine Igf1 and Igfbp3 after stroke." (PMID 35557964, 2022). "However, a recent study demonstrated that microglia is a dominant target of IGF-1 in the stroke mice." (PMID 36062186, 2022). "Proliferating microglia and astrocytes express Igf1 after stroke." (PMID 35557964, 2022). "Additionally, reduced paracrine cerebral Igfbp3 increases the amount of active unbound Igf1 in the brain, which is known to improve outcome after stroke." (PMID 35557964, 2022). "In humans, growing evidence shows effects of endocrine Igf1 and Igfbp3 after stroke." (PMID 35557964, 2022). "IGF1 also protects neurons from brain injury, stroke, and neuroinflammatory response." (PMID 35313975, 2022). "Paracrine Igf1 is brain cytoprotective and improves functional recovery after stroke." (PMID 35557964, 2022). "After stroke, Igf1 blood levels were significantly increased in Zfp580 knockout mice." (PMID 35557964, 2022). "Post-stroke administration of IGF-1 is neuroprotective after stroke." (PMID 33584250, 2021). "For example, a bout of exercise on a treadmill produced intensity-dependent increases in brain-derived neurotrophic factor (BDNF) and vascular endothelial growth factor (VEGF) in serum, and, to a lesser extent, insulin-like growth factor 1 (IGF-1), in stroke patients." (PMID 33917909, 2021). "While many studies associate reduced IGF-1 with increased neurodegeneration, some clinical studies of dementias and stroke see increased IGF-1 levels at the start of pathology, which may be an attempted compensatory mechanism designed to protect the brain." (PMID 34887742, 2021). "If manipulation of circulating IGF-1 levels at the acute phase of dMCAO can affect disease outcome, future therapeutic strategies may be contemplated in this direction for treatment of stroke." (PMID 32952570, 2020). "IGF-1 gene therapy can reduce the reactivity of astrocytes in response to proinflammatory stimuli in vitro and exert neuroprotective and neuroreparative actions in experimental animal models of hypoxia and stroke." (PMID 32952570, 2020). "Insulin like growth factor-1 is demonstrated to be neuroprotective after brain trauma or stroke." (PMID 31338023, 2019). "Moreover, post-stroke treatment with systemically injected IGF-1 induced neuroprotection in several rat models for ischemic stroke." (PMID 31920629, 2019). "This notion is also supported by a study, in which IGF‐1 improves stroke recovery aged female rats." (PMID 31747126, 2019). "In addition, exogenous IGF-1 has been found to protect the cerebral parenchyma in stroke models and to result in improved neurological outcomes." (PMID 31338023, 2019).